WNT5A (Wnt family member 5A)
Diseases named in the same sentence as WNT5A in open-access papers (continued):
Sharing a sentence is not in itself a finding about the gene and the disease.
tumor (continued). "In certain situations, non-canonical Wnt5a has shown to be tumor suppressive and promote differentiation, most likely via cross-inhibition of canonical Wnt signaling (Zhou, Kipps, & Zhang, 2017)." (PMID 35358569, 2022). "Due to the high levels of WNT5A in DHSF-BR16 cell line, it may represent a relevant tumor model for an in-depth study of the WNT5A signaling." (PMID 33863935, 2021). "In contrast to our previous findings, where tumor‐derived WNT5A was corresponding with FZD5 and RYK receptor no interrelation of these receptors to stWNT5A was observed in this study." (PMID 33639039, 2021). "In contrast, Rspo2 appears to inhibit CRC metastasis by competing with the tumor-promoting Wnt5a for binding to Fz7 and thus antagonizing Wnt5a-driven non-canonical Wnt signaling." (PMID 33585487, 2021). "Tumor-derived factors, such as TGF-β and prostaglandin E2 (PGE2), alter pDC functionality by inhibiting their ability to produce type I IFN, and tumor cells expressing Wnt5a inhibit pDC activation and IFN-α secretion." (PMID 34290401, 2021). "The results suggested that decreased WNT5A expression, together with increased MMP9 expression, in icSFT/HPC, may affect vascular tightness and prompt tumor cells to metastasize extracranially." (PMID 33799999, 2021). "IHC of WNT5A in extracranial metastatic lesions revealed none-to-weak positivity but MMP9 IHC showed occasional tumor cells with strong cytoplasmic immunoreactivity." (PMID 33799999, 2021). "The oncogenic and tumor suppressor effects of Wnt5a on the different stages of CRC suggest that Wnt5a noncanonical signaling can be used as an attractive candidate target for this disease." (PMID 34603445, 2021). "WNT5a can also specifically activate the TLR/MyD88/p50 pathway in bone marrow monocytes and promote the synthesis of anti-inflammatory cytokines such as IL-10 and the tolerance phenotype, thus forming an immunosuppressive tumor microenvironment." (PMID 34565373, 2021). "Indeed, among several cytokines that regulate the tumor-bone interaction and were upregulated significantly more by KLF5KQ than by KLF5KR (SHH, WNT5A, IL11, and IL6), the induction of IL-11 was dependent on CXCR4 expression." (PMID 33731701, 2021). "We have demonstrated that ascites in many patients are capable of inducing WNT signaling in tumor cells and also shown that tumors exhibit alterations in the expression level of WNT/PCP components which may explain their sensitivity to WNT5A." (PMID 31903136, 2020). "Wnt5a, a ligand that activates the non-canonical branch of the Wnt pathway, can play a role as a tumor suppressor or by promoting cancer cell invasion and migration, although the molecular mechanisms explaining these roles have not been fully elucidated." (PMID 32195251, 2020). "Intriguingly, we found that Wnt5a was mainly expressed in the tumor stroma, especially in TAMs, with no or scarce expression in tumor nest." (PMID 32228612, 2020). "Additionally, Ki67 staining, an indicator of tumor proliferation, also decreased in the HCT116 + sh-Wnt5a TAMs group compared with HCT116 + sh-NC TAMs group." (PMID 32228612, 2020). "Although Wnt5a was an important mediator for TAMs to support tumor, it did not directly affect CRC cells." (PMID 32140070, 2020). "Wnt5a is involved in mediating noncanonical signaling via FZD or ROR receptors and has been associated with both oncogenic and tumor-suppressive effects, as discussed in other reviews." (PMID 33126517, 2020). "The CCK-8 and colony formation assay analyses showed that tumor cell proliferation was not affected by knockdown of Wnt5a, as well as tumor cell migration." (PMID 32228612, 2020). "Our data indicate that Wnt5a could induce M2 polarization of TAMs by regulating CaKMII-ERK1/2-STAT3 pathway–mediated IL-10 secretion, ultimately promoting tumor growth and metastasis of CRC." (PMID 32228612, 2020).
tumor (continued). "Furthermore, Wnt5a-induced M2 macrophages promoted CRC cells proliferation, migration and invasion; knockdown of Wnt5a in TAMs significantly impaired the pro-tumor functions of TAMs." (PMID 32228612, 2020). "Together, these data demonstrate that Wnt5a does not directly promote tumor progression, and is not a macrophage chemokine." (PMID 32140070, 2020). "Collectively, these studies demonstrate that cortactin plays a critical role in ROR1-dependent, noncanonical Wnt5a signaling, leading to increased tumor-cell migration and metastasis." (PMID 31667337, 2019). "Therefore, we mainly tested the anti-tumor effects of four representative agents in HMSM, including anti-WNT5A antibody, PLX3997, Anti-IL-2 antibody (IL-2 neutralization), and EGFR inhibitor." (PMID 31504033, 2019). "Comparing with Anti-IL-2 and EGFR inhibitor, a combination of castration with Anti-WNT5A or PLX yields better anti-tumor responses, indicating that blockade of the PC-Treg or PC-TAM interaction may effectively reduce tumor cell growth." (PMID 31504033, 2019). "In this work, we identified the pro‐tumorigenic function of FOXM1 by inhibiting maturation and antitumor response of bone marrow‐derived dendritic cells (BMDCs) in tumor‐bearing mice (TBM) and mimicking the tumor microenvironment (TME) through FOXM1‐Wnt family number 5A (Wnt5a) signaling." (PMID 30628173, 2019). "In the meantime, the reduced methylation status of DACT2, Wnt5A, and SFRP2 promoter was detected in TET1-CD-expressing tumor cells, with increased unmethylated sites at the promoter CpG regions, suggesting that TET1 really acts as a demethylase to renew expression of multiple TSGs in tumor cells." (PMID 30075814, 2018). "Our findings demonstrate that miR-129-5p acts as a tumour suppressor, mediating the inhibition of proliferation, invasion, migration, neurosphere formation, angiogenesis and TMZ resistance by suppressing its target, Wnt5a." (PMID 29531296, 2018). "Activation of the noncanonical pathway by Wnt5a has been shown to be involved in tumor growth and invasion." (PMID 29465811, 2018). "We then examined transcriptional activation of WNT5A promoter in normal liver cells, peri-tumor cells, non-TICs and TICs, and found WNT5A promoter is specifically activated in non-TICs." (PMID 29535420, 2018). "We observed weak Wnt5a expression in non-tumor ductal epithelial cells but none in basal or stromal cells." (PMID 29765514, 2018). "During ErbB2-induced mammary tumorigenesis, basal tumor-initiating cells (TIC), which exhibited enhanced tumorigenic capacity compared with the corresponding luminal progenitors, preferentially lost Wnt5a expression, as determined by transcript profiling analysis." (PMID 28491097, 2017). "Wnt5a is a noncanonical member of the Wnt protein family and promotes oncogenesis and tumor metastasis." (PMID 28380463, 2017). "Activation or inhibition of Wnt5a signaling, a member of the noncanonical Wnt signaling pathways has been described as an important event in pathogenesis of cancer as tumor suppressor or tumor promoter, in a variety of malignancies." (PMID 28427201, 2017). "Among the rather limited set of stromal-derived secreted factors in our detergent-extracted matrisomes, IGF2 and Wnt5A (a non-canonical Wnt ligand) were present in the matrix of both tumour-derived fibroblast preparations." (PMID 28102238, 2017). "Wnt5a, a non-transforming Wnt family member, plays complicated roles in oncogenesis and cancer metastasis, exerting both oncogenic and tumor suppressive effects." (PMID 29213214, 2017). "To determine the expression of Wnts in non-CRC cell types in the tumor grafts, we sorted host-derived endothelial cells, fibroblasts, macrophages and dendritic cells and tested mRNA levels of Wnt3, Wnt3a, Wnt5a and Wnt10a in these cells." (PMID 28147310, 2017).
tumor (continued). "Overall, we demonstrated that WNT5A signaling (via a β-catenin-PFKP axis) reduces lactate production and lowers the expression of MCT1, a carrier mediating the uptake of lactate from the tumor microenvironment." (PMID 29069720, 2017). "Suppression of UBE2T inhibited Wnt5A and WNT7B, thus inhibiting tumor growth." (PMID 28427240, 2017). "PCa cells also express factors such as TGFβ (transforming growth factor beta), WNT family members such as Wnt5a and the pro-angiogenic factor VEGFA that promote an aggressive tumor phenotype and bone metastases by directly affecting osteoclast and osteoblast formation." (PMID 27776343, 2016). "We observed the expression of Wnt5a and Ror2 in PTL tumor tissues by immunohistochemistry." (PMID 26608372, 2016). "As WNT-5A antagonizes WNT/β-catenin signaling, it is tempting to speculate that it functions as tumor suppressor in WNT/β-catenin-dependent cancers provided it activates the downstream cascade involved in this antagonism." (PMID 26514730, 2016). "While further studies are required to elucidate a clear role of WNT-5A in CRC, it is tempting to speculate that WNT-5A acts as a tumor suppressor in β-catenin-dependent stages of CRC progression." (PMID 26514730, 2016). "Adherent confluent Mel8 cells express higher level of WNT5a, TCF4 and VEGF and lower level of LEF1 at mRNA level than sub-confluent cells suggesting that these cells are prone to phenotype switch, simulating in vitro tumor spreading." (PMID 27175588, 2016). "Interestingly, analysis of circulating tumor cells (CTC) from patients had indicate that WNT5A is activated, in keeping with a role for WNT5A in cell polarization and cancer cell invasion." (PMID 27776343, 2016). "Wnt5a signaling plays a less well-characterized role in tumor development but is understood to act via non-canonical, β-catenin-independent, Wnt signaling pathways." (PMID 27500936, 2016). "By using IWP-2, the inhibitor of Wnt/β-catenin pathway, and Wnt5a siRNA, we found that ART, DHA, and ARTS could render tumor inhibition partially dependent on Wnt/β-catenin inactivation." (PMID 27119499, 2016). "Only three tumor biopsies showed increased ABCB1 expression without concurrent increases in Wnt5A after chemotherapy." (PMID 25401518, 2014). "Multiple lines of evidence suggest that the non-canonical Wnt, Wnt5a, functions as a tumor suppressor protein." (PMID 25401739, 2014). "Multiples lines of clinical evidence suggest that Wnt5a, a non-canonical signaling Wnt, can act as a tumor suppressor." (PMID 25401739, 2014). "In addition, they only reported the relationship between Wnt5a and MVD, which only reflected the endothelial dependent vessel in the tumor." (PMID 24999479, 2014). "Katoh has suggested that the non-canonical pathway is involved in tumor cell invasion and metastasis, but studies investigating the role of wnt5a expression in cancer have been limited and controversial." (PMID 24564183, 2014). "Wnt expression at the metastatic site was rare if the primary tumor tested negative for both wnt3a and wnt5a." (PMID 24564183, 2014). "Initially, Wnt5a was found to be a non-transforming member of the Wnt family, but subsequently, it was found that its acts as a tumor suppressor in human cancers." (PMID 23349696, 2013). "Wnt5a was methylated in 27 of these tumours (17 MSI, 10 MSS) and no methylation was found in matched normal tissue." (PMID 21587258, 2011). "Wnt5a methylation was absent from a subset of matched normal mucosa, verifying that this event is tumour specific." (PMID 21587258, 2011). "For example, Wnt5a can mediate migration via PKC activation, by inducing an epithelial to mesenchymal transition (EMT), by inhibiting metastasis suppressors such as matrix metalloproteases and by regulating expression of tumor antigens via STAT3." (PMID 21494614, 2011).
tumor (continued). "Using immunohistochemistry we detected the presence of a K6 population of cells in PyVmT tumours in the absence of Wnt5a, suggesting an expansion of this population in the tumours." (PMID 19344510, 2009). "Our results suggest that Wnt5a, upregulated in poorly differentiated highly motile mesenchymal-like HCC cells may play a role in tumor progression by inducing EMT." (PMID 19849855, 2009). "In the absence of Wnt5a, tumour volume was approximately two-fold greater than control MMTV-PyVmT tumours at the time of sacrifice." (PMID 19344510, 2009). "MMTV-PyVmT tumours, in the absence of Wnt5a also contained an expanded myoepithelial lineage, marked by K14." (PMID 19344510, 2009). "It is also interesting that Wnt5A has been found to inhibit B cell proliferation and can function as a tumor suppressor in hematopoietic tissue, albeit via the non-canonical Wnt/Ca2+ pathway." (PMID 16808837, 2006). "Cells treated with recombinant Wnt5a demonstrated a decrease in both ALCAM and vinculin, supporting the hypothesis that the interaction of these two proteins is affected by Wnt5a in the tumor microenvironment." (PMID 41301074, 2025). "The interaction between FZD2 and non-canonical Wnt ligands, such as Wnt5a, may vary across different cancer types, influencing its functional role in tumor progression." (PMID 40444048, 2025). "In addition to Wnt3A and Wnt1, upregulation of Wnt3A, Wnt4, Wnt5A, and Wnt10B has also been observed in both tumor tissue and the adjacent non-tumorous liver." (PMID 40943055, 2025). "Additionally, Wnt5a drives tumor cell invasion via the non-canonical Wnt pathway, engaging PKC, CDC42 or JNK/c-JUN signaling cascades." (PMID 40399946, 2025). "However, a separate and compelling body of evidence has shown that in the unique microenvironment of the bone, Wnt5a secreted by osteoblasts acts via ROR2 to suppress canonical Wnt/β-catenin signalling, thereby inducing a state of dormancy in disseminated tumour cells." (PMID 41007281, 2025). "From a therapeutic perspective, targeting the molecular components of the “Black” module, such as WNT5A, EPHA2, and EGFR, could offer promising strategies to counteract tumor invasiveness and overcome drug resistance, particularly in Cluster B patients, who may be more responsive to such inhibitors." (PMID 41465101, 2025). "Moreover, the upregulation of miR26a could restore Enz sensitivity in vitro and in vivo, synergistically suppressing tumor growth, bone metastasis, and secondary metastasis by regulating the EZH2/SFRP1/WNT5A axis." (PMID 38566211, 2024). "Also, CAFs-derived WNT5A elevated HK2 expression and promoted GC tumor growth in vivo." (PMID 39054546, 2024). "However, the expression of pro-tumorigenic genes including Ang4, VEGF, Wnt5a and MMP-10 was comparable in the LRRK2 KI and WT control groups, suggesting that LRRK2 G2019S may promote tumor development primarily by promoting inflammation." (PMID 38607004, 2024). "Interestingly, a weak WNT5A up-regulation was observed in the M13HS-2 and -8 ZEB1-KO tumor hybrids." (PMID 38139138, 2023). "Indeed, Wnt ligand signaling plays a key role in PDAC progression and therapeutic resistance, and tumor-proximal fibroblasts are seen to be strong contributors to the Wnt ligand pool with high level expression of the ligands WNT5A, WNT11, WNT2, WNT5, WNT5A, and WNT5B." (PMID 37350578, 2023). "Furthermore, in postnatal retinas and tumours, noncanonical Wnt5a, facilitated by the Wnt secretion factor, contributes to the activation of Wnt signalling." (PMID 38136392, 2023). "Wnt Family Member 5A (Wnt5a) is one of the crucial members of the non-classical Wnt family and participates in many physiological and pathological processes, such as tissue fibrosis, tumours and other diseases." (PMID 37255814, 2023). "In addition, WNT5a in NSCLC cells could increase the expression of β-catenin and VEGF-A in stromal cells through tumor-stroma interaction, thus promoting tumor angiogenesis." (PMID 37486552, 2023).
tumor (continued). "However, circulating miR-155, miR-410, and miR-181a/b showed a negative correlation with tumor suppressive gene WNT5A (p < 0.0001, r = -0.671) and with oncogenes MET (p < 0.0001, r = -0.4778), EGFR (p < 0.0001, r = -0.5235, r = -0.5217)." (PMID 35646622, 2022). "In the MOLT-4 xenotransplants the tumor cell liver infiltrates had a distinct pattern from the infiltrations observed in Jurkat-derived xenografts; their distribution and shape is fully compatible with the previously reported on SCID xenografts of MOLT-4 cells treated with CCL25+Wnt5a." (PMID 35967322, 2022). "Moreover, analyses of SOX10– and SOX10+MITF– tumors developed in NSG mice at molecular level suggested a profound difference between the tumor types and reflected the tumor growth difference and sustained increased expression of NGFR, JUN, and WNT5A in the SOX10+MITF– melanoma tumors." (PMID 36040798, 2022). "Since the tumor suppressors such as phosphatase and tensin homolog (PTEN) and Wnt5a have a highly conserved binding site for miR-26b, transfection of miR-26b mimic into the CRC cell lines stimulates metastasis of CRC cells via increasing EMT and downregulation of Wnt5a and PTEN." (PMID 34603445, 2021). "Moreover, qRT-PCR verified seven apoptosis-related genes (APP, DOCK8, IFI44, MDK, SLC27A2, TNFAIP2, WNT5A) with at least 2 fold changes by means of 2−ΔΔCt method, finding that APP, SLC27A2 and WNT5A had a low expression, while DOCK8, IFI44, MDK, TNFAIP2 had a high expression in ccRCC tumor tissues." (PMID 33748185, 2021). "Recent findings demonstrate that Wnt5a noncanonical ligand, as a tumor suppressor and oncogenic agent, can promote and inhibit tumor processes through canonical and noncanonical Wnt signaling in many common cancers such as colorectal breast, prostate, ovarian, bladder, and lung cancer." (PMID 34603445, 2021). "Consistently, treating mice with Wnt5a, the critical pro-angiogenic factor regulated by FOSL2, could partly rescue blood vessels and tumor growth of tumor burden mice injected with FOSL2-silenced CAFs (labeled CAF/shFOSL2 + rWnt5a) in comparison to their control tumors (labeled CAF/shFOSL2)." (PMID 33754039, 2021). "Here, we found that Wnt5a was mainly expressed on TAMs of tumor stroma but not on CRC cells." (PMID 32140070, 2020). "We observed that Wnt5a was primarily localized in the tumor stroma but not on tumor cells." (PMID 32140070, 2020). "The PTK7, which interacts with Wnt5A, LRP6 and FZD7, may act as a tumour suppressor or oncogene." (PMID 33080952, 2020). "However, the deregulation of WNT5A promotes an oncogenic or tumor suppressor effects through canonical and non-canonical signaling pathways." (PMID 31213644, 2019). "Once a dose has been decided, one could then evaluate the efficacy of Foxy5 in combination, sequentially or simultaneously, with conventional therapies in the treatment of cancer patients with a low or no expression of the WNT5A protein in their primary tumor." (PMID 30171384, 2018). "In order to study the effects of Foxy-5 on tumor growth and metastatic spreading in vivo, immunodeficient NMRI nude mice were injected orthotopically with cells expressing low levels of WNT5A (DU145-Luc) or with cells expressing higher levels of WNT5A (PC3M-Luc2)." (PMID 28886116, 2017). "Expression of Wnt5A can activate a non-canonical Wnt pathway and suppress the signal of the canonical Wnt pathway, resulting in decreased proliferation, migration, invasiveness, and clonogenicity of cells, therefore behaving as a tumor suppressor." (PMID 28027300, 2016). "Therefore, with or without Wnt5a, the irreplaceable and sustained suppression of Wnt/β-catenin pathway occurred, suggesting that the anti-tumor effects of ART and its derivatives only partially depended on Wnt5-a/b inactivation." (PMID 27119499, 2016).